IL10 (interleukin 10)
Diseases named in the same sentence as IL10 in open-access papers (continued):
Sharing a sentence is not in itself a finding about the gene and the disease.
rheumatoid arthritis (continued). "After that, the low-dose cytokine combination [IL-4, IL-10, and anti-IL-1 antibodies (10 fg/mL)] therapy also exhibited the promising prospect in rheumatoid arthritis, at a randomized, open, active-controlled, prospective, phase IV trial." (PMID 37492521, 2023). "For example, in rheumatoid arthritis products from the gut microbiota drive the production of IL-1β and IL-6 which in turn promotes the differentiation of IL-10+ Bregs." (PMID 37600781, 2023). "We reported that butyrate ameliorated SS by inducing interleukin-10 (IL-10)-producing B cells and attenuated rheumatoid inflammation in an animal model of rheumatoid arthritis." (PMID 37316856, 2023). "Previously, LMNB1 mRNA was increased following IL-10 stimulation of rheumatoid arthritis synovial macrophages, suggesting a possible anti-inflammatory role, a feature that has been supported in other models." (PMID 36050729, 2022). "Studies have explored the potential of recombinant IL-10 as a treatment for autoimmune disease, most extensively in rheumatoid arthritis (RA)." (PMID 35296082, 2022). "One report has demonstrated a regulatory role of Dnaja1 where it inhibits T cell proliferation and induces IL‐10 production by PBMC in rheumatoid arthritis patients." (PMID 36030499, 2022). "In rheumatoid arthritis (RA), WKYMVm stimulates IL-10 production by acting on FPR1 which is expressed on the surface of mature dendritic cells (DCs)." (PMID 36120322, 2022). "Previous studies show that rheumatoid arthritis patients display lower serum levels of IL-10 compared to healthy patients." (PMID 36362383, 2022). "Abundant papers have proved anti-inflammatory response of IL-10 brings new hope for many immune diseases, such as autoimmune encephalomyelitis, crohn’s disease, ulcerative colitis and rheumatoid arthritis." (PMID 36369030, 2022). "An imbalance between the proinflammatory cytokines and anti-inflammatory cytokines, such as IL-10 and IL-4, precipitates inflammatory disease conditions, including rheumatoid arthritis." (PMID 35248062, 2022). "In the animal model of rheumatoid arthritis (RA), helminth therapy with S. mansoni and S. japonicum showed attenuation of disease severity via up-regulation of IL-4 and IL-10." (PMID 34451389, 2021). "Different studies found that serum levels of IL-10 in rheumatoid arthritis-suffering patients was lower than that found in healthy people, but some pro-inflammatory factors, such as IL-17, IL-1β and TNF-α, were higher." (PMID 33796536, 2021). "A similar pattern was demonstrated in rheumatoid arthritis between IL-10-producing B cells and rheumatoid factor (RF) or anti-citrullinated protein antibodies (ACPA)." (PMID 34681587, 2021). "Anastrozole increased the production of proinflammatory cytokines like IFN-γ, IL-12 and decreased IL-4 and IL-10 cytokine secretion in an animal model that simulates human rheumatoid arthritis." (PMID 33530456, 2021). "Perhaps not increased systemic levels of IL-10, but local expression of IL-10 is important, as seen in studies on rheumatoid arthritis, where local administration of IL-10 to sites of inflammation was protective, but systemic application was not." (PMID 33584677, 2020). "As a representative example, tissue-resident macrophages in the lining layer of inflamed joints express higher levels of IL-10 than infiltrating macrophages during rheumatoid arthritis." (PMID 32532019, 2020). "The anti-inflammatory cytokine interleukin-10 with its cell mediated immune response and anti-inflammatory action has vast potential in treating inflammatory, autoimmune disorders and rheumatoid arthritis." (PMID 33178550, 2020). "Consistent with our observations, IL-10 induction has also been considered a mechanism underlying the suppressive effect of MAT in several other inflammatory disorders, such as rheumatoid arthritis, neuropathic pain, and nephropathy." (PMID 33101289, 2020).
rheumatoid arthritis (continued). "Consistent with the reported negative regulatory function of the Breg cells, significantly lower levels of IL10+ Breg cells were observed in rheumatoid arthritis patients." (PMID 32775471, 2020). "IL-10 is a potent anti-inflammatory cytokine that has been shown to regulate endogenous pro-inflammatory cytokine production in synovial tissues from rheumatoid arthritis subjects." (PMID 32595650, 2020). "It has been shown that the methotrexate treatment reduces the TNFα, IL1β, and IL6 production and increases the IL10 expression in the synovial tissue of rheumatoid arthritis patients." (PMID 31958219, 2020). "These DEGs were enriched for immune-related pathways including rheumatoid arthritis, granulocyte adhesion, IL10, and NFKB signaling." (PMID 32579111, 2020). "Treatment of rheumatoid arthritis (RA) patients with two capsules of Nigella sativa oil (500 mg, per day for 8 weeks) significantly increased IL-10 serum level, whereas it decreased serum levels of MDA and nitric oxide compared with the placebo group." (PMID 33062002, 2020). "C5orf30 was also shown to inhibit the generation of cytokines involved in inflammation, such as TNF and IL1, and promote the expression of anti-inflammatory cytokines, such as IL10, in rheumatoid arthritis synovial fibroblasts." (PMID 30705370, 2019). "Patients with rheumatoid arthritis treated with Abatacept show increased IL-10 by producing CD4+CD25-LAG3+ Treg cells." (PMID 31582900, 2019). "Elevated expression of Hsp60 has been reported to correlate with the production of IL-10 and IL-4 which suppress the severity of rheumatoid arthritis." (PMID 30388847, 2018). "IL-10 is a typical anti-inflammatory cytokine:its influence on the course of rheumatoid arthritis is considered as favorable,since it inhibits the action of autoimmune Th17 and reduces IL-17 production byimmune cells, preventing joint destruction." (PMID 30397522, 2018). "Clinical trials have reported that IL-10 is effective in treating inflammatory diseases, including Crohn’s disease and rheumatoid arthritis." (PMID 29497350, 2018). "Lactobacillus casei also suppresses the development of rheumatoid arthritis by upregulating IL-10 expression." (PMID 29760423, 2018). "IL-10 has been identified as one possible inducer for intermediate monocytes in rheumatoid arthritis; this cytokine is highly upregulated in supernatants from MDM stimulated with corneal tissue." (PMID 29617399, 2018). "IL-10 concentration correlated with depressive symptoms in patients with rheumatoid arthritis (p = 0.005, OR = 1.13), in that higher IL-10 levels correlated with more depressive symptoms." (PMID 30148175, 2018). "We aimed to clarify the function of human IL-10-producing CD4+CD25−LAG3+ T cells (LAG3+ Tregs) and their association with rheumatoid arthritis (RA)." (PMID 28511719, 2017). "In mice with rheumatoid arthritis, there is an increase in IL-10, and this cytokine is one of the primary factors that is responsible for the development of severe forms of dengue." (PMID 28100218, 2017). "LILRA5 expression has been described for macrophages and induces production of proinflammatory cytokines and IL-10 in a rheumatoid arthritis model." (PMID 27654936, 2016). "Previous studies with IL-10 gene therapy in experimental models of rheumatoid arthritis have explored the use of inducible promoters to drive the expression of IL-10." (PMID 27519904, 2016). "Significantly decreased IL-10+ B-cell frequency has also been described in patients with rheumatoid arthritis." (PMID 26016954, 2015). "F8-IL10 is a human immunocytokine based on the F8 antibody and interleukin-10, which is currently being investigated in rheumatoid arthritis with promising clinical results." (PMID 24289726, 2013). "The application of IL-10 as therapy has already been investigated in diseases such as psoriasis or rheumatoid arthritis." (PMID 22855687, 2012).
rheumatoid arthritis (continued). "Based upon IL-10's potent immune-suppressive activity in cell culture and animal models, the potential of recombinant IL-10 in treating inflammatory diseases such as Crohn's disease and rheumatoid arthritis has long been considered." (PMID 22087322, 2011). "Exogenous IL-10 can suppress the in vitro development of Th17 cells from CD4+ T cells in patients with rheumatoid arthritis." (PMID 22176654, 2011). "The anti-inflammatory cytokine IL-10 has been investigated for the treatment of patients with rheumatoid arthritis, but clinical development plans have been discontinued because of a lack of efficacy." (PMID 17261171, 2007). "Despite its potent ability to inhibit proinflammatory cytokine synthesis, interleukin (IL)-10 has a marginal clinical effect in rheumatoid arthritis (RA) patients." (PMID 16859503, 2006). "IL‐10 deficiency is associated with increased tissue damage, and in diseases like rheumatoid arthritis, an endogenous immunological control mechanism enhances IL‐10 production, promoting repair‐related events and reducing the sensitization of sensory nerve endings." (PMID 41006957, 2025). "IL‐10 is abundantly expressed in the synovial fluid of patients with rheumatoid arthritis." (PMID 41006957, 2025). "Moreover, a recent study conducted on rheumatoid arthritis synoviocytes showed that octreotide suppresses production of interleukin (IL)‐15 and increases IL‐10,30 both components of the immune pituitary adenoma TME." (PMID 40789673, 2025). "In addition, they induced interleukin 10 secretion by synovial fluid cells in rheumatoid arthritis and gout patients." (PMID 38601165, 2024). "IL-10 meanwhile, has not been shown to be directly involved in the polarization of Tregs but has well established effects on the activation and proliferation of Tregs with the blocking of IL-10 in a mouse model of rheumatoid arthritis sufficient to prevent the immunosuppressive impact of Tregs." (PMID 37063900, 2023). "The in vitro treatment of peripheral blood mononuclear cells of patients with rheumatoid arthritis with HSP70 induces the production of IL-10, and Mycobacterium tuberculosis HSP70 (mtHS70) blocks the maturation of bone marrow precursors that fail to express MHC class II and CD86." (PMID 36830641, 2023). "Increased levels of IL-4, IL-6, TNF-α, IL-10, and IL-17 have been reported in rheumatoid arthritis." (PMID 37111383, 2023). "Additionally, similar to other forms of rheumatoid nodules, higher levels of IL-1, together with IL-12, IL-18, IL-15, and IL-10, have been reported in pulmonary rheumatoid nodules." (PMID 37238933, 2023). "In vitro treatment of peripheral blood mononuclear cells of patients with rheumatoid arthritis with HSP70 induce the production of IL-10 and Mycobacterium tuberculosis HSP70 (mtHS70) blocks the maturation of bone marrow precursors that fail to express MHC class II and CD86." (PMID 36830641, 2023). "Estrogen, which is crucial for female immunity, is thought to act as a protective mechanism against rheumatoid arthritis and Sjogren’s syndrome because higher levels can reduce inflammation by increasing regulatory cytokines like interleukin-10 (IL-10) and transforming growth factor- (TGFB)." (PMID 38105265, 2023). "What is more, previous studies have reported that the expression levels of IL6 and IL10 are downregulated in patients with rheumatoid arthritis however, in our research we have found that mitotransfer significantly enhanced their amount on mRNA and protein levels." (PMID 36071528, 2022). "L. fermentum PC1 has a treatment potential against rheumatoid arthritis in the murine model of collagen-induced arthritis through the attenuation of proinflammatory cytokine IL-12 and the augmentation of anti-inflammatory cytokines IL-4 and IL-10." (PMID 35601147, 2022).
rheumatoid arthritis (continued). "Koffeman and collaborators (2009) tested the oral administration of 25 mg dnaJP1 peptide in rheumatoid arthritis patients for 6 months reporting a reduction in TNF-alpha-producing T cells and an increase in IL-10-producing Treg cells associated with amelioration of disease." (PMID 35919733, 2021). "Contrary to studies on other autoimmune conditions, such as rheumatoid arthritis, Foxp3+ and IL-10+ Bregs were not negatively associated with autoantibodies in Graves’ patients." (PMID 34681587, 2021). "A potentially disease-protective effect of MDSC was reported in a murine model of multiple sclerosis (MS), where MDSC inhibited autoreactive Th1 and Th17 responses or in rheumatoid arthritis (RA) where MDSC reciprocally regulate Th17/T regs via IL-10 production." (PMID 33206686, 2020). "We now show that the transcriptome of human macrophages from healthy and inflamed tissues (tumor; rheumatoid arthritis, RA) share a significant over-representation of the “anti-inflammatory gene set”, which defines the gene profile of M-CSF-dependent IL-10-producing human macrophages (M-MØ)." (PMID 32532019, 2020). "Hypermethylation of CpG islands in the IL-10 promoter region may be involved in the development of rheumatoid arthritis (RA)." (PMID 32582189, 2020). "Orally administered HY7801 regulates immune biomarkers, including TNF-α, IFN-γ, IL-17A, IL-10, and IL-12, and might be useful in the treatment of rheumatoid arthritis." (PMID 32384794, 2020). "Rheumatoid arthritis synovial macrophages exhibit characteristics of IL10- or IFNγ-stimulation." (PMID 31921150, 2019). "In line with this hypothesis, recent findings show that locally produced IL-10 is implicated in MDSC activation in an S. aureus biofilm infection model and in a collagen-induced model of rheumatoid arthritis." (PMID 30123776, 2018). "In patients with rheumatoid arthritis, anti-TNF therapy has been incredibly effective in treating disease, response to this therapy is associated with the induction of Treg that can secrete IL-10 and TGFβ to control inflammatory responses." (PMID 29176976, 2017). "The present study addressed the question whether in patients with rheumatoid arthritis (RA) interleukin-10 (IL-10) promoter genotypes with potential relevance for IL-10 production capacity are associated with response to long-term treatment with etanercept." (PMID 26107717, 2015). "Furthermore, systemic toxicities of IL-10 have been thoroughly characterized in trials of recombinant IL-10 for Crohn disease, rheumatoid arthritis, Wegener granulomatosis, and psoriatic arthritis." (PMID 25183392, 2014). "Similarly, in group 2, which mainly consisted of HuGE-pathways, IL-6 and IL-10 signaling pathways were observed and found to be connected through the pathway “role of macrophages, fibroblasts and endothelial cells in Rheumatoid Arthritis”." (PMID 21390307, 2011). "Leukaemia inhibitory factor, inducible through IL-1β and loaded on the same component together with IL-1β and IL-10, has been shown to have parallels with IL-1, tumour necrosis factor-α and IL-6 within the context of promoting inflammation in rheumatoid arthritis." (PMID 18289371, 2008). "Additionally, Prakken and colleagues have demonstrated induction of IL-10-secreting Treg following oral peptide therapy in patients with rheumatoid arthritis." (PMID 15783262, 2005). "Early clinical trials investigated the use of recombinant IL-10 protein for the treatment of rheumatoid arthritis (RA), psoriasis, and Crohn’s disease (CD), but with limited effectiveness." (PMID 41357227, 2025). "levels in the intestines of rheumatoid arthritis (RA) patients and model mice, positively correlated with the frequency of circulating IL-10+ Bregs." (PMID 41562083, 2025).
rheumatoid arthritis (continued). "Furthermore, the upregulation of COLEC11 may provide a new strategy for treating rheumatoid arthritis and other inflammatory diseases by promoting the expression of the anti-inflammatory factor IL-10 and suppressing the activation of antigen-presenting cells." (PMID 40705171, 2025). "Another study reported that HSP60 prevents inflammation-induced cell death in rheumatoid arthritis (RA) via secretion of anti-inflammatory cytokines IL-4 and IL-10 at the inflammation site in the bone." (PMID 38673794, 2024). "A high concentration of anti-inflammatory IL-10 is observed in serum rheumatoid arthritis RA; high in serum and cerebrospinal fluid in NMOSD, high in culture supernatants LPS-stimulated neutrophils isolated from DM1 patients." (PMID 38745328, 2024). "With rheumatoid arthritis RA, when Th1 cells are treated with statins, activation of the cholesterol biosynthesis pathway causes them to switch from IFN-γ to IL-10+." (PMID 38921447, 2024). "Notably, following the systemic administration of GRP78 or its analog IRL201805 in an animal model of rheumatoid arthritis, these proteins are rapidly internalized by monocytes, which eventually leads to an increased secretion of IL-10 and the suppression of TNF-α and IL-1β release." (PMID 38612761, 2024). "A previous study reported that macrophage-derived EVs and potent anti-inflammatory immune modulator interleukin-10 were integrated by electroporation for the treatment of rheumatoid arthritis (RA)." (PMID 37362216, 2023). "The down-regulation of CD39 in these naïve B cell populations in TN patients may also contribute to such potential escape of autoreactive B cells from regulatory mechanisms like CD39-mediated immune regulation, a phenomenon also described in rheumatoid arthritis, or IL-10 production." (PMID 35799782, 2022). "IL-4 and IL-10 have been tested for their anti-inflammatory and chondroprotectiveeffects for the treatment of rheumatoid arthritis (RA); however, results wereinconsistent." (PMID 35549461, 2022). "IL-10 secretion is increased in the synovial fluid of Rheumatoid arthritis (RA), accompanied by abnormal neutrophil autophagy." (PMID 36263059, 2022). "It has been demonstrated that CD14+CD16+ intermediate monocytes are induced by IL-10 and positively correlate with disease activity in rheumatoid arthritis (RA)." (PMID 33488616, 2020). "A study on rheumatoid arthritis showed that high-dose silibinin significantly reduced inflammatory markers (ESR, IL-8, IL-6, TNF-α, anti-CCP) and increased Hb, IL-10, and IL-2, compared to placebo." (PMID 39850538, 2025). "Octreotide (OCT)—which is a first-generation SSA—modulates cytokine production in rheumatoid arthritis synoviocytes through interleukin-15 and TNF-α inhibition and increases interleukin-10 levels." (PMID 40732232, 2025). "In patients with rheumatoid arthritis, rituximab significantly reduced serum concentrations of CRP, RF, anti-CCP, IL-2, IL-6, IL-7, IL-10, and ESR." (PMID 41057909, 2025). "For example, stigmasterol treatment reduced TNF-α, IL-6, IL-1β, iNOS and COX-2 in collagen-induced rheumatoid arthritis (RA) rats, and increased the expression of anti-inflammatory cytokines (IL-10) by down-regulating NF-kB p65 and p38 MAPK expression in the joints." (PMID 38579176, 2024). "We aimed to investigate the expression of pro-inflammatory cytokine genes TNFA, IL6, IL12B, IL23, IL18 and immunoregulatory genes FOXP3, TGFB1, and IL10 in the peripheral blood of patients with rheumatoid arthritis (RA) at messenger ribonucleic acid (mRNA) level." (PMID 38534783, 2024). "The potential core targets for Mugua treatment of rheumatoid arthritis are IL-6, TNF, IL-1β, and IL-10." (PMID 39705460, 2024). "Specifically, it decreases the production of several cytokines, including IL-17, IL-6, IL-10, and TNF-α, as well as IFN-γ in rheumatoid arthritis (RA) patients and induces Tregs in certain experimental models." (PMID 38791521, 2024).